TNF (tumor necrosis factor)
Diseases named in the same sentence as TNF in open-access papers (continued):
Sharing a sentence is not in itself a finding about the gene and the disease.
Hypertension (continued). "Increased circulating levels of pro-inflammatory cytokines (PICs) including Tumor necrosis factor alpha (TNF-α), Interleukin-6 (IL-6), and Interleukin-1 beta (IL-1β) have been noted in both human hypertension and animal models of hypertension." (PMID 29520237, 2018). "Together, these data suggest that TNF-induced hypertension is mediated by ET-1, through ETA receptor activation." (PMID 28264495, 2017). "Hypertension is associated with the infiltration of T cells into the kidney and vasculature, with the release of cytokines, including IFN-γ and TNF-α, which promote sodium retention, vasoconstriction, and oxidative injury." (PMID 29082259, 2017). "VD possesses the potential of serving as a safe and effective adjuvant to oral nifedipine in treating women with preeclampsia against hypertension, possibly through the upregulation of IL-10 and the downregulation of TNF-α." (PMID 29225576, 2017). "AT1R inhibition has proven to reduce inflammation in hypertension, as well as LPS-induced inflammation, via the reduction of IL-1β, IL-6 and TNFα levels." (PMID 28416734, 2017). "It has also been shown that infusion of TNF-α alone induces hypertension in pregnant rats, producing an approximate 20 mmHg increase in MAP in late gestation." (PMID 28264495, 2017). "It is logical to assume that similar effects of intestinal flora and NAFLD also exist, since TNFα is the key mediator of inflammation and so hypertension in this disease." (PMID 28507473, 2017). "Tumour necrosis factor-α (TNF-α) as an inflammatory marker induces angiotensin II (Ang II) related hypertension pathway in diabetic patients." (PMID 29391930, 2017). "Recently a considerable body of evidence showed that inhibition of TNF-α expression can inhibit hypertension related vascular remodeling, inflammation and oxidative stress." (PMID 29391930, 2017). "Recently, it has become evident that the immune system and inflammatory markers such as Interleukin-6, Tumor necrosis factor alpha and C-reactive protein are also essential in the pathogenesis of hypertension." (PMID 26989902, 2016). "We examined if intrarenal TNFα contributed to hypertension in SS rats by treating uninephrectomized SS rats with renal interstitial infusion of the TNFα inhibitor Etanercept." (PMID 26916681, 2016). "Previous investigations also confirm that serum levels of IL-6, IL-8, TGF-β and TNF-α were altered in the patients suffering from hypertension and CAD." (PMID 28033321, 2016). "T cell-produced cytokines (such as tumor necrosis factor alpha, or TNFα) and many of the interleukins (such as IL-6) have been shown to play a role in hypertension." (PMID 27092251, 2016). "Renal interstitial administration of Etanercept, an inhibitor of TNFα, significantly attenuated the development of hypertension in SS rats on a high-salt diet (n = 7–8, p < 0.05)." (PMID 26916681, 2016). "We then examined the contribution of intrarenal TNFα to hypertension by infusing Etanercept directly and locally into the renal interstitium." (PMID 26916681, 2016). "Angiotensin-converting enzyme 2 (ACE2) overexpression in the PVN has also been shown to attenuate both ANG II-induced hypertension and expression of the pro-inflammatory cytokines TNFα, IL-1β, and IL-6 in the PVN43." (PMID 27092251, 2016). "The downstream mechanism by which renal TNFα contributes to hypertension in SS rats also remains to be investigated." (PMID 26916681, 2016). "TNF-α is a well-known inflammatory cytokine and appears to have an important role in hypertension and renal fibrosis." (PMID 26121471, 2015).
Hypertension (continued). "The ischemic placenta induces activation of peripheral T cells, which can directly promote the development of hypertension by production of cytokines such as TNF-α and IL-6 and the anti-angiogenic factor sFlt-1 and by stimulating B cells to produce AT1-aa." (PMID 26569331, 2015). "We also investigated the role of TNF-α inhibition on activation of MAPK signaling in Ang II-induced hypertension and cardiac hypertrophy." (PMID 26378790, 2015). "In the present study, we showed that the plasma levels of CRP, IL-6 and TNF-α were significantly increased in acute TAAD patients (before T6) compared to those in uncontrolled hypertension and healthy volunteers." (PMID 25592634, 2015). "Although it has been suggested that several cytokines are involved in vascular damage induced by hypertension, TNF-α inhibition decreases blood pressure and prevents target organ damage in animal studies." (PMID 26504819, 2015). "Here, we have attempted to examine directly the effects of HO-1 induction in a TNF-α infusion model of hypertension in rodents during late gestation." (PMID 26347650, 2015). "It has been well established that sympathetic hyperactivity contributes to cardiac remodeling in hypertension via an increase in TNF-α production and NFκB activation leading to end organ damage." (PMID 25879545, 2015). "In order to further confirm the role of TNF-α in Ang II-induced hypertension and cardiac hypertrophy, mice were treated with etanercept during saline or Ang II infusion for 14 days." (PMID 26378790, 2015). "The cytokines TNF-α, IL-6 and IL-17 can themselves produce hypertension when infused into pregnant rats." (PMID 26569331, 2015). "HO-1 induction has been shown to be protective and anti-hypertensive in several experimental models of hypertension, including the reduced uterine perfusion pressure (RUPP) model, known to be associated with elevated TNF-α levels." (PMID 26347650, 2015). "AngII induced renal inflammation and hypertension is mediated by interleukin 6 (IL-6), and characterized by increased expression of tumor necrosis factor (TNF)-α, and monocyte chemoattractant protein-1 (MCP-1)." (PMID 26121471, 2015). "Blockade of TNF-α has been shown to delay the progression of salt sensitive hypertension, prevent the development of hypertension in fructose fed rats, and decreased hypertension in a mouse model of systemic lupus erythematosus." (PMID 26378790, 2015). "Together, these findings indicate that TNF-α contributes to Ang II-induced hypertension and adverse cardiac remodeling, and that these effects are associated with changes in the oxidative stress dependent MAPK/TGF-β/NF-κB pathway." (PMID 26378790, 2015). "The findings from this study contribute to our understanding of the cellular signaling mechanisms of TNF-α in Ang II-induced hypertension and cardiac remodeling." (PMID 26378790, 2015). "Overactivity of the proinflammatory cytokines such as TNF-α and IL-1β in the PVN, a critical cardiovascular and autonomic center, has been implicated in the development and the maintenance of hypertension and heart failure." (PMID 25885968, 2015). "Previous studies from this and other laboratories have shown that inhibition of TNF-α was involved in attenuating Ang II mediated hypertension." (PMID 26378790, 2015). "Due caution for hypertension and nephrotoxicity is important when using cyclosporine A; instead reactivation of tuberculosis has to be considered when using TNF-alpha antagonists." (PMID 26558256, 2015). "The functional crosstalk between angiotensin II (Ang II) and tumor necrosis factor (TNF)-α has been shown to cause adverse left ventricular remodeling and hypertrophy in hypertension." (PMID 26378790, 2015). "In these animals, the inhibition of TNF-α prevented increased vascular superoxide production and hypertension mediated by angiotensin II." (PMID 26504819, 2015).
Hypertension (continued). "Risk factors that associate with intracranial aneurysm such as hemodynamic stress, hypertension, and smoking are also known to induce the production of TNFα." (PMID 26198819, 2015). "Previous studies have demonstrated high levels of CCL2 in patients with arterial hypertension, as well as increased levels of TNF-α on DOCA-salt models." (PMID 25878716, 2015). "A growing body of evidence indicates that hypertension is an inflammatory state wherein proinflammatory cytokines, such as tumour necrosis factor-alpha (TNF-α) and interleukin-6 (IL-6), contribute to the hypertensive effect." (PMID 26055622, 2015). "Within the PVN, TNF-α and IL-1β increased renal sympathetic nerve activity and blood pressure while chronic blockade of TNF-α and NF-κB inhibited hypertension-induced cardiovascular effects." (PMID 24788542, 2014). "Inflammation has been considered a key component in the pathogenesis of hypertension which is a low-grade inflammatory condition induced by TNFα." (PMID 24665369, 2014). "We have previously found that induced hypertension in conjunction with hemodynamic stress in rats in vivo can increase the expression of TNF-α." (PMID 24739142, 2014). "MAPKs are activated in response to inflammatory and atherogenic stimuli, such as PDGF-BB, TNF-α, oxidative stress, hypertension, and balloon injury, and stimulate the expression of several inducible proteins." (PMID 25114952, 2014). "In summary, serum ZAG and HMW adiponectin levels are significantly lowered, while TNFα greatly increased in hypertension patients." (PMID 24665369, 2014). "In previous studies performed in our cohort of AS patients undergoing anti-TNF-α therapy, we found that ADMA levels were associated with features of MeS, such as hypertension." (PMID 25295265, 2014). "This cytokine has been directly correlated to hypertension because the activation of the AT1 receptor induces TNF-α secretion; it is also well known that this cytokine is cytotoxic to villous trophoblast cultures." (PMID 25574467, 2014). "In an animal study on pregnant rats, reductions in uterine perfusion pressure (RUPP) led to an increase in plasma TNF-α levels and induction of hypertension." (PMID 24719701, 2014). "Treatment with 40 mg/kg 4HCH reduced systolic hypertension, serum IL-1β, and TNF-α levels and suppressed the activation of nuclear factor kappa-light-chain-enhancer of activated B cells (NF-κB) and renal injury." (PMID 25003119, 2014). "In the present study, the role of central TNF on Ang II-induced hypertension and cardiac hypertrophy was investigated." (PMID 23691105, 2013). "Bautista reviewed multiple studies and reported a positive association between hypertension and some proinflammatory markers including C-reactive protein (CRP), interleukin-6 (IL-6), and tumor necrosis factor alpha (TNF-α)." (PMID 23691280, 2013). "Our findings provide further evidence and insight for the involvement of the RAS within the PVN and its interaction and mediation through TNF in the neurogenic component of hypertension." (PMID 23691105, 2013). "Our findings demonstrate that the changes observed in Ang II-induced hypertension are regulated, at least in part, through the central actions of TNF and potentially via the dysregulation of components of the RAS within the hypothalamic PVN." (PMID 23691105, 2013). "These PICs were attenuated in the PVN of Ang II-infused rats treated ICV with etanercept, demonstrating that chronic Ang II infusion increases the pro-inflammatory response within the PVN through TNF in Ang II-induced hypertension." (PMID 23691105, 2013). "Recent evidence suggests that hypertension is an inflammatory condition where various PICs such as TNF, IL-6 and IL-1β, both centrally and peripherally, have been shown to play an important role in the pathogenesis of hypertension." (PMID 23691105, 2013).
Hypertension (continued). "Both in vitro and in vivo studies have demonstrated a cross-talk between Ang II and TNF, a mechanism we have also shown using TNF knockout mice where Ang II-induced hypertension was attenuated via a decreased expression of AT1R." (PMID 23691105, 2013). "Although several PIC are upregulated in hypertension, we have focused on TNF, since it is generally the first cytokine that is upregulated in disease and since it also induces the production of several other cytokines." (PMID 23056347, 2012). "Increased TNF-α concentrations were observed in pregnant women with preeclampsia (hypertension with proteinuria) when compared with those with gestational hypertension (hypertension without proteinuria)." (PMID 22462002, 2012). "Intraperitoneal infusion of LPS (1.2 mg/kg/day) for 14 days promoted sustained hypertension and induced a significant increase in plasma level of C-reactive protein, tumor necrosis factor-α (TNF-α), or interleukin-1β (IL-1β)." (PMID 22958438, 2012). "Our data demonstrated a significant increase in the plasma sICAM-1 levels in the early stage of hypertension and a significant upregulation of the NFκB p65/TNF-α pathway in the established stage." (PMID 22736937, 2012). "We found that vagus nerve function was decreased after 2K1C surgery (i.e. at 4, 8 and 20 weeks of age); expression of α7nAChR was downregulated in aorta (from 4 weeks) and kidney (from 8 weeks), and serum TNF-α was increased in 2K1C hypertension." (PMID 22682236, 2012). "The TNF-α-induced migration of monocytes in patients with essential hypertension was also significantly increased compared to normotensive control subjects (221±20% vs 138±18%)." (PMID 22438881, 2012). "TNF-α functions as a mediator of inflammatory reactions and plays a part in the immunopathogenesis of hypertensive disease." (PMID 22142875, 2012). "In angiotensin II-infused mice, serum levels of IL-17A, IL-23, and TNF-α, which have roles in maintaining hypertension, were shown to be significantly increased, while serum levels of the anti-inflammatory factor IL-10, which has cardiovascular protective effects, were significantly decreased." (PMID 40028265, 2025). "Indeed, previous studies showed that innate and adaptive immunity participate to cardiovascular diseases and hypertension by the production of pro-inflammatory cytokines such as TNF-alpha, IFN-gamma and IL-17A." (PMID 40303366, 2025). "Body weight exhibited the highest mediation at 30.3% (95% CI: 3.85%-56.75%), followed by IL-17 (17.2%; 95% CI: 2.01%-38.78%), TNF (14.08%; 95% CI: 2.23%-35.10%), coronary atherosclerosis (13.4%; 95% CI: 4.89%-23.98%), and hypertension (11.6%; 95% CI: 2.45%-21.51%)." (PMID 39988492, 2025). "Both TNF-α and IL-6 have been shown to directly contribute to the development of hypertension." (PMID 39484785, 2025). "In well-controlled hypertension, inflammatory markers, including TNF-α and IL-6, were comparable to those in normotensive subjects, suggesting that effective blood pressure management may normalize systemic inflammatory activity." (PMID 41440524, 2025). "In addition, hypertension significantly enhanced the expression of TNF-α of mice in the PFC, hippocampus, and hypothalamus after 12 w Pb exposure." (PMID 39853035, 2025). "The potential mechanisms may include: oxidative stress and chronic inflammation: hypertension induces vascular endothelial damage, promoting pro-inflammatory cytokines (such as TNF-α, IL-6) and reactive oxygen species release." (PMID 41398846, 2025). "Inflammatory cytokines such as IL- 6 and TNF-α, elevated in acne, also play a role in hypertension." (PMID 40358870, 2025). "In this context, an elevated IL-6/TNF-α ratio may act synergistically with dysregulated vasoactive pathways, amplifying vascular dysfunction and sustaining postoperative hypertension." (PMID 41010423, 2025).
Hypertension (continued). "In addition, hypertension resulted in higher TNF-α protein expression in the PFC, hippocampus, and hypothalamus of mice at 4 w, 8 w, and 12 w exposure, respectively." (PMID 39853035, 2025). "Compared with the control group TNF-α (1.11 ± 0.42); Compared with IL-6 (1.1 ± 0.49), TNF in lymphocytes of hypertensive patients-α (1.42 ± 0.72); The expression of IL-6 (1.48 ± 0.68) gene showed an increasing trend in the hypertensive patient group, with no statistical significance (P > .05)." (PMID 41366965, 2025). "The dietary approaches to stop hypertension score (DASH-S) demonstrated a significant positive association with adiponectin and an inverse association with CRP in early pregnancy and other proinflammatory biomarkers (TNF-α and IL-6)." (PMID 40043850, 2025). "Once activated, microglia could secrete cytokines, such as IL-1α, TNFα, and complement component 1q (C1q), that—in turn—induce astrocyte activation, as it has been shown in experimental longer-lasting arterial hypertension." (PMID 39495252, 2024). "TNF-α has also been thought to play a role in hypertension in male SHRs." (PMID 39599656, 2024). "DeGT is as effective as RGT in treating various MS-related factors, including energy intake, fat mass, hypertension, serum L/A ratio, serum corticosterone and 11βHSD1 in adipose tissue, TNF-α in adipose tissue, adipocyte hypertrophy, enlargement of Bowman’s space area and glomerular atrophy." (PMID 39598339, 2024). "TNF‐α has many adverse effects, one of which is leading to hypertension." (PMID 39479630, 2024). "miR-146a regulates transcription factor nuclear factor kappa B (NF-κB), which activates the transcription of proinflammatory genes, such as interluekin-6 and tumor necrosis factor α, thus increasing the inflammatory load and has been shown to be elevated in hypertension." (PMID 38396672, 2024). "Furthermore, hypertension with hypercholesterolemia increased the expression of TNF-α, IL-6, and IL-1β levels in renal tissues and was inhibited by treatment with Egb761." (PMID 39065815, 2024). "Based on previous studies, α-MG can reduce circulating TNF-α levels in acute liver injury and acute kidney injury, and our current work further indicated that α-MG may directly target TNF-α in Ang II-induced hypertension." (PMID 39592923, 2024). "It has been found that NF-κB can mediate a variety of inflammatory responses, and activation of the NF-κB signaling pathway induces an increase in the expression of TNF-α and IL-6, which leads to hypertension and contributes to the development of cardiac remodeling." (PMID 38680497, 2024). "However, further clinical studies on the effect of TNFα inhibition on hypertension are needed in order to understand its clinical therapeutic potential." (PMID 38256155, 2024). "Elevations in pro-inflammatory cytokines, such as interleukin (IL)-6, IL-1β, IL-1α, IL-18, IL-2, IL-8, tumor necrosis factor (TNF)-α, interferon (IFN)-γ, C-reactive protein (CRP), and monocyte chemoattractant protein (MCP)-1, have been associated with arterial hypertension." (PMID 39519450, 2024). "TNF-α may contribute to hypertension by increasing the synthesis of angiotensin-converting enzyme (ACE)." (PMID 38672199, 2024). "The pleiotropic nature of TNFα was highlighted in hypertension." (PMID 38256155, 2024). "The results indicate that in the Ang II-induced hypertension group, the expression levels of TNF, NFKB1, MAPK3, PTGS2, and RELA were markedly elevated compared to the control group, while the expression levels of HSP90AA1, HSP90AB1, PPARG, SIRT1, MAPK1, and PRKCA were significantly decreased." (PMID 39592923, 2024). "W1302 may suppress hypoperfusion with hypertension-induced learning impairments through the NO-regulated NF-κB signaling pathway, decrease the expression of TNF-α, and preserve mitochondrial function." (PMID 38790690, 2024).